PVT1 (Pvt1 oncogene)
Diseases named in the same sentence as PVT1 in open-access papers (continued):
Sharing a sentence is not in itself a finding about the gene and the disease.
glioma (63 papers, 2014 to 2025). A benign or malignant brain and spinal cord tumor that arises from glial cells (astrocytes, oligodendrocytes, ependymal cells). "The results indicated that higher PVT1 expression was associated with aggressive progression of glioma." (PMID 37202742, 2023). "The underlying mechanism provides a basis for PVT1 as a new molecular target for treatment of glioma." (PMID 37202742, 2023). "Glioma with higher PVT1 expression was significantly associated with the somatic mutation of PTEN, EGFR and TTN." (PMID 37202742, 2023). "Similar results were well validated in CGGA and GSE16011 cohorts and indicated higher PVT1 expression level always associated with the higher malignance of glioma." (PMID 37202742, 2023). "Some, SOX2-OT, ZFAS1, SAMMSON, CASC19/PCAT2, and PVT1, have already been associated with various cancers, including gliomas." (PMID 35852875, 2022). "As a subfamily of long non-coding RNA, plasmacytoma variant translocation 1 (PVT1) is often linked to oncogenesis of malignant cancers including a brain tumor, glioma." (PMID 34521353, 2021). "Of importance to glioma, PVT1 has been implicated in regulating levels the proto-oncogene MYC to promote tumorigenesis." (PMID 33926464, 2021). "lncRNA plasmacytoma variant translocation 1 (PVT1) is upregulated in human glioma tissues and cell lines and functions as a miRNA sponge, binding to miR-128-3p." (PMID 34202078, 2021). "Autophagy: PVT1 overexpression increased expression of autophagy-associated proteins, namely Atg7 and Beclin1, by inhibiting miR-187 in glioma vascular endothelial cells." (PMID 34322395, 2021). "For instance, lncRNA Plasmacytoma variant translocation 1 (PVT1) facilitates glioma by targeting miR-128-3p/Gremlin-1 (GREM1) axis." (PMID 32398968, 2020). "The present study aimed to investigate the potential roles of PVT1 in the development of glioma and to elucidate its underlying mechanism." (PMID 29046366, 2017). "Similarly, lncRNA PVT1 (plasmacytoma variant translocation 1), was shown to facilitate tumourigenesis and glioma progression via the regulation of bone morphogenetic protein (BMP) signaling pathway." (PMID 33800703, 2021). "H19 had been associated with glioblastoma and PVT1 had been associated with glioma." (PMID 24498199, 2014). "Additionally, we investigated PVT1's role in influencing glioma‐associated macrophages." (PMID 38287522, 2024). "Finally, high PVT1 expression was associated with reduced survival time and may serve as a strong prognostic indicator for gliomas." (PMID 37202742, 2023). "This confirmed the expression of MiR17hg, SNHG6, H19 and Pvt1 in glioma-infiltrating immune cells, consistent with our murine models." (PMID 40527978, 2025). "Various lncRNAs were found to be aberrantly expressed in glioma, such as lncRNA PVT1, lncRNA BCYRN1 and lncRNA DGCR5." (PMID 38730506, 2024). "Within the same grade of gliomas, the expression level of PVT1 in glioma of IDH wild type was notably higher than that in the ones of mutant type." (PMID 38287522, 2024). "We assessed aberrant PVT1 expression in glioma tissues and its impact on GBM cell growth in vitro and in vivo." (PMID 38287522, 2024). "Multivariate Cox regression analysis of the prognostic performances of differentially expressed lncRNAs identified H19 and plasmacytoma variant translocation 1 (PVT1) as risky lncRNAs and highly accelerated region 1A (HAR1A) as a protective lncRNA in glioma." (PMID 36819921, 2023). "Our results indicated that higher PVT1 expression was closely related with glioma malignant progression and chemotherapy resistance." (PMID 37202742, 2023).
glioma (continued). "To investigate the role of PVT1 in tumors, we compared the expression pattern of PVT1 between normal tissues and tumor, and found that PVT1 was highly expressed in glioma and many malignancies." (PMID 37202742, 2023). "In CGGA cohort, the Kaplan-Meier analysis verified that gliomas with higher expression levels of PVT1 experienced significantly shorter overall survival (OS) in both whole gliomas (p < 0.0001) and GBM (p = 0.0064)." (PMID 37202742, 2023). "This study was the first integrative study to characterize PVT1 expression in glioma in clinical and molecular aspects." (PMID 37202742, 2023). "To explore the relationship between PVT1 and clinicopathology characteristics, we arranged glioma samples according to the ascending order of PVT1 expression in three independent cohorts." (PMID 37202742, 2023). "Meanwhile, the amplification of EGFR and CDK4, and the deletion of PTEN and CDKNA2A/B were observed in the gliomas with high PVT1 expression." (PMID 37202742, 2023). "To explore the mechanism of action of PVT1 in tumor progression in glioma, we investigated the distinct genomic alternations in order of increasing PVT1 expression." (PMID 37202742, 2023). "Meanwhile, glioma in mesenchymal and classical (p < 0.0001) molecular subtypes had higher PVT1 expression." (PMID 37202742, 2023). "In this study, we gathered genomic and transcriptomic profiles from three independent cohorts (TCGA, CGGA and GSE16011) to comprehensively depict the role of PVT1 in gliomas." (PMID 37202742, 2023). "Then we explored the distribution characteristics of PVT1 expression in glioma, according to WHO grade, IDH status, 1p/19q status and molecular subtype." (PMID 37202742, 2023). "Initially, lncRNA PVT1 expression was increased in glioma clinical samples from patients at WHO stage I, WHO stage II and WHO stage III while an ascending trend was observed over the staging." (PMID 35275031, 2022). "Specifically, PVT1 reportedly promotes glioma cell proliferation, invasion, metastasis, and EMT by upregulating GREM1, PTBP1, TMBIM6, HNF1B, and Atg7/Beclin1 by modulating miR-128-3p, miR-128-1-5p, miR-1301-3p, miR-1207-3p, and miR-186, respectively." (PMID 36195846, 2022). "Another study came to a similar conclusion that PVT1 acted as a sponge of miR-200a and promoted glioma proliferation and invasion." (PMID 36195846, 2022). "Knockdown of lncRNA PVT1 attenuated glioma cell proliferation, invasion, and migration in vitro and produced smaller tumours in a mouse model." (PMID 33800703, 2021). "For example, LncRNA PVT1 promotes tumorigenesis and glioma progression by regulating the miR-128-3p/GREM1 axis and BMP signaling pathway." (PMID 34408982, 2021). "PVT1 promotes tumorigenesis and cancer progression of glioma via regulation of miR-128-3p/GREM1 Axis and BMP signaling pathway." (PMID 34950662, 2021). "In the light of the role of PVT1, there are studies implying that overexpressed PVT1 shows up in glioma and diffuse gliomas." (PMID 34521353, 2021).
glioma (continued). "For example, high expression of PVT1 in the nucleus can accelerate glioma cell proliferation, invasion, and aerobic glycolysis by inhibiting the expression of miR-140-5p17." (PMID 34131250, 2021). "Compared with non-tumor brain tissues, the expression levels of SNAI3-AS1, GDNF-AS1, WDFY3-AS2, and CPB2-AS1 showed an overall downward trend, and the expression level of SBF2-AS1, PAXIP1-AS2, SNHG18, and PVT1 showed an overall upward trend in glioma tissues." (PMID 34095147, 2021). "Several studies, including investigations of large datasets, found higher PVT1 expression in glioma tissue and cell lines than normal." (PMID 34322395, 2021). "Zhang et al21 revealed that lncRNA PVT1 expression was upregulated in glioma and that silencing of lncRNA PVT1 induces G0/G1 cell cycle arrest and suppresses cell invasion and proliferation." (PMID 32960485, 2021). "Prognostic value: Higher expression of PVT1 was an indicator of poor prognosis and survival in glioma." (PMID 34322395, 2021). "A recent study found that lncRNA PVT1 was upregulated in glioma vascular endothelial cells and miR-186 was downregulated." (PMID 33029125, 2020). "LncRNA PVT1 promoted glioma tumorigenesis and progression by targeting miR-128-3p/GREM1 axis and regulating BMP signaling pathway." (PMID 32009853, 2020). "For instance, PVT1/miR-190a-5p-miR-488-3p/MEF2C signaling was indicated to affect the development of human glioma." (PMID 33185692, 2020). "For example, recurrent translocations of PVT1-MYC or PVT1-NDRG1 were identified in a large study on medulloblastoma, the most malignant brain tumor in children, or genomic amplifications of MYC/PVT1 in pediatric gliomas." (PMID 31781490, 2019). "PVT1 can promote the development of glioma cells through various mechanisms, resulting in a worse prognosis for patients with glioma and high PVT1 expression." (PMID 31309249, 2019). "Knocking down PVT1 significantly reduced tumor volume in bladder, prostate, breast, and lung cancer, as well as hepatocellular carcinoma and glioma." (PMID 31249809, 2019). "All together, these results suggested that high PVT1 expression and low HAR1A expression were associated with poor survival outcome of glioma patients." (PMID 29108264, 2017). "The current study revealed that PVT1 expression levels in glioma were significantly higher than in normal brain tissue and that the high PVT1 expression levels correlated with patients’ poor overall survival." (PMID 29046366, 2017). "Then, we investigated the potential effects of PVT1 on glioma cell proliferation and invasion using two kinds of glioma cell lines." (PMID 29046366, 2017). "The present study aimed to assess the relationship between plasmacytoma variant translocation 1 (PVT1) and enhancer of zeste homolog 2 (EZH2), and their effects on the proliferation and invasion of glioma cells." (PMID 29046366, 2017). "However, the underlying role and molecular mechanism of PVT1 in glioma remain unclear." (PMID 29046366, 2017). "Then, after siRNA-PVT1 and entire PVT1 sequence vector transfection, we determined the regulation roles of PVT1 in the proliferation, apoptosis, migration, and invasion of glioma cells." (PMID 29046366, 2017). "In our study, we found that EZH2 expression levels were positively correlated with glioma malignancy and with poor prognosis in glioma tissue samples, which is the same as for PVT1." (PMID 29046366, 2017). "Our studies first identified differentially expressed lncRNAs in glioma based on gene expression profiling, and focused on the lncRNAs PVT1, CYTOR, HAR1A and MIAT for further analysis." (PMID 29108264, 2017). "Within glioma samples of TCGA along with LGG subtypes, the overall survival of glioma patients with high PVT1 expression was remarkably worse than that of the low expression patients (both P <0.0001)." (PMID 29108264, 2017).
glioma (continued). "This study focused on identifying differentially expressed lncRNAs in gliomas based on gene expression profiling, and chose certain lncRNAs PVT1, CYTOR, HAR1A and MIAT, which changed with significant differences." (PMID 29108264, 2017). "Combined with the previous research, these results suggest that the level of PVT1 expression significantly regulates the tumorigenesis of glioma cells in vivo." (PMID 29046366, 2017). "To explore the role of PVT1 in glioma cells, we stably silenced PVT1 with siRNA-PVT1, and overexpressed PVT1 with entire PVT1 sequence vector respectively in U87MG and U251 cells." (PMID 29046366, 2017). "Furthermore, in gliomas, lncRNA PVT1 binds specifically to miR‐128‐1‐5p, affects the expression of the miR‐128‐1‐5p target gene PTBP1, promotes apoptosis of glioma cells, and inhibits their proliferation." (PMID 40579921, 2025). "Pvt1, significantly expressed in MDSCs, was upregulated in microglia, BAMs and macrophages, but downregulated in immunosuppressive Int Mo/Mac and in GAMs, suggesting a potential role in myeloid cell infiltration in glioma." (PMID 40527978, 2025). "PVT1: The lncRNA PVT1 is highly expressed in gliomas and correlates with aggressive progression." (PMID 40896358, 2025). "Additionally, PVT1 regulated CX3CL1, recruiting M2‐polarized glioma‐associated macrophages, and promoting an immunosuppressive microenvironment." (PMID 38287522, 2024). "Furthermore, we found the expression level of PVT1 correlated with molecular grading, serving as an indicator of poor prognosis in gliomas." (PMID 38287522, 2024). "For instance, PVT1 has been found to regulate the immunosuppression activity of myeloid-derived suppressor cells (MDSCs), which inhibit the cytotoxic responses mediated by natural killer cells and blocked T cell-induced antitumor responses in glioma 47,48." (PMID 37056564, 2023). "However, there are few studies on the investigation the prognostic significance and clinical features of PVT1 in gliomas." (PMID 37202742, 2023). "In addition, glioma patients with high PVT1 expression or low HAR1A expression is reported to be prognostic of poor survival in glioma patients." (PMID 36819921, 2023). "As depicted above, PVT1 participated in regulating JAK/STAT signaling in glioma." (PMID 37202742, 2023). "We further experimentally verified the functional roles of PVT1 in glioma in vitro." (PMID 37202742, 2023). "In addition, we found that patients with higher expression of PVT1 had a significantly shorter overall survival for glioma patients in each cohort." (PMID 37202742, 2023). "In addition, this study indicated that PVT1 promoted glioma TMZ chemoresistance through JAK/STAT signaling." (PMID 37202742, 2023). "Exploring and revealing the mechanism of PVT1 in glioma may develop the therapeutic approaches to overcome this disease." (PMID 37202742, 2023). "We found that several lncRNAs, namely, AL606760.2, H19, MALAT1, PVT1 and SBF2-AS1 may function as glioma risk factors, whereas AC068643.1, AC079228.1, DGCR5, FAM13A-AS1, HAR1A and WDFY3-AS2 may have protective effects." (PMID 36819921, 2023). "Taken together, we elaborated the roles of PVT1 in glioma from transcriptomic and genomic levels." (PMID 37202742, 2023). "Notably, H19, MALAT1, PVT1, and SBF2-AS1 have been associated with temozolomide resistance in glioma patients." (PMID 36819921, 2023). "Besides, the higher expression of PVT1 was detected in IDH wildtype (p < 0.0001) or 1p/19q (p < 0.0001) intact glioma, which involved in the malignant progression of glioma." (PMID 37202742, 2023). "We hypothesized that PVT1 was a crucial regulator of JAK/STAT pathway in glioma, which in line with previous research in bronchial asthma." (PMID 37202742, 2023). "The results verified that PVT1 played an important role in the malignancy of glioma and may serve as a potential therapeutic target for glioma patients." (PMID 37202742, 2023).
glioma (continued). "Furthermore, the qPCR experiment of glioma patients (WHO II–IV grade) showed that PVT1 was the highest in WHO IV patients and lowest in WHO II patients (p < 0.0001)." (PMID 37202742, 2023). "We found that PVT1 was hypo-methylated, thus elevating its expression in glioma C1 patients." (PMID 37056564, 2023). "PVT1 is a known oncogene in various cancers, including glioma." (PMID 36819921, 2023). "Taken together, these studies demonstrate that PVT1 is an oncogene in glioma and may be a target for future therapy." (PMID 36195846, 2022). "So in gliomas, UPF1 could not only act with LncRNA PVT1 to aggravate the progression of glioma but can bind circRPPH1 to help strengthen the malignant phenotype." (PMID 35871061, 2022). "These experimental data suggested high lncRNA PVT1 expression in glioma tissues and cells." (PMID 35275031, 2022). "In the recent years, some emerging evidence has suggested that silencing PVT1 could inhibit malignant biological behaviors of glioma cells." (PMID 34475987, 2021). "Angiogenesis: Glioma vascular endothelial cells had a higher PVT1 expression." (PMID 34322395, 2021). "Only a few studies have evaluated the prognostic role of PVT1 SNPs in glioma." (PMID 34322395, 2021). "lncRNA PVT1 and miR-186 would provide an antiangiogenic target for gliomas." (PMID 33029125, 2020). "Our analysis indicated that JAG1, PVT1, H19, and HAR1A were aberrantly expressed in IDH mutant gliomas and were core lncRNA genes in regulating the expression of protein-encoding gene in IDH mutant gliomas." (PMID 33329315, 2020). "PVT1 was found to be highly expressed in glioma vascular endothelial cells." (PMID 30266744, 2018). "In the present study, the PVT1 expression levels of four glioma grades showed that it was positively correlated with glioma malignancy, and may play an important role in glioma progression, and may be useful as a prognostic indicator for malignant glioma." (PMID 29046366, 2017). "The present study’s results showed that PVT1 knockdown could significantly inhibit glioma cell proliferation and invasion, and PVT1 overexpression could conversely induce cell proliferation and invasion both in vitro and in vivo." (PMID 29046366, 2017). "Survival analyses indicated that glioma patients with low PVT1 expression and high HAR1A expression could benefit more from chemotherapy and radiotherapy." (PMID 29108264, 2017).